RNU6-1250P (RNA, U6 small nuclear 1250, pseudogene)
Gene: Small nuclear RNA gene on chromosome 10 (67,808,502 to 67,808,608, forward strand). Ensembl gene ENSG00000212520.
Homologues: Orthologues: chimpanzee U6 (96% identical), macaque U6 (86% identical), rat LOC120094555 (81% identical), rabbit U6 (80% identical). Paralogues in human: RNU6-116P (80% identical), RNU6-1243P (79% identical), RNU6-797P (79% identical), RNU6-1060P (79% identical), RNU6-1094P (79% identical), RNU6-1331P (79% identical), RNU6-34P (79% identical), RNU6-41P (79% identical), RNU6-48P (79% identical), RNU6-727P (79% identical), RNU6-748P (79% identical), RNU6-879P (79% identical), and 1284 more.